INSR (insulin receptor)
Diseases named in the same sentence as INSR in open-access papers (continued):
Sharing a sentence is not in itself a finding about the gene and the disease.
depression (continued). "Importantly, this drug and another insulin receptor sensitizer, pioglitazone, were recently reported to be effective for the treatment of a major depressive disorder that was refractory to standard antidepressant treatment and accompanied by insulin resistance." (PMID 22989159, 2012). "And mice with a brain-specific knockout of the insulin receptor (NIRKO mice) exhibit the age-related anxiety and depression-like behaviors." (PMID 34149862, 2021).
type B insulin resistance (16 papers, 2015 to 2026). "Type B insulin resistance syndrome (TBIRS) is a rare autoimmune condition characterized by insulin receptor autoantibodies, often in association with systemic lupus erythematosus (SLE)." (PMID 42211865, 2026). "Type B insulin resistance syndrome is caused by AIRAs, which, based on rodent and cellular studies, act as agonists at the insulin receptor when the titre is low and as antagonists due to receptor downregulation when at high titre." (PMID 32755965, 2020). "The syndrome of type B insulin resistance is caused by circulating autoantibodies against the insulin receptor." (PMID 25675382, 2015). "Type B insulin resistance is a very rare disease caused by autoantibodies against the insulin receptor." (PMID 25675382, 2015). "Type B insulin resistance is caused by autoantibody directed against the insulin receptor." (PMID 27142369, 2016). "Type B insulin resistance syndrome (TBIR) is a rare autoimmune disorder characterised by the development of anti-insulin receptor antibodies (AIRA)." (PMID 32755965, 2020). "Type B insulin resistance is a rare autoimmune disease characterized by the presence of autoantibodies against the insulin receptor." (PMID 27142369, 2016). "Type B insulin resistance syndrome (TBIRS) is an especially rare autoimmune disorder with unknown prevalence, caused by immunoglobulin G polyclonal antibodies that antagonize the insulin receptor." (PMID 32813762, 2020). "Besides, the diagnosis of type B insulin resistance was confirmed by the presence of insulin receptor antibody." (PMID 27142369, 2016). "Type B insulin resistance syndrome (TBIRS) is rare, with an unknown prevalence, characterized by antibodies directed against the insulin receptor." (PMID 41767203, 2026).
endothelial dysfunction (15 papers, 2012 to 2026). In vascular diseases, endothelial dysfunction is a systemic pathological state of the endothelium (the inner lining of blood vessels) and can be broadly defined as an imbalance between vasodilating and vasoconstricting substances produced by (or acting on) the endothelium. "Elevated SUA can lead to oxidative stress, endothelial dysfunction, inflammation and impaired function of adipocytes—all of which collectively impede insulin receptor activity and downstream signalling." (PMID 41521685, 2026). "Mechanistically, high SUA levels can lead to oxidative stress, endothelial dysfunction, inflammation, and impaired function of adipocytes—all of which collectively impede insulin receptor activity and downstream signaling." (PMID 41521685, 2026). "In ECs, downregulation of the insulin receptor-Akt1 signaling pathway leads to endothelial dysfunction and an increase in the entry of inflammatory cells into plaques." (PMID 40144296, 2025). "Several studies identified protein tyrosine phosphatase (PTP)-1B, a member of the PTP superfamily, as a major negative regulator for insulin receptor signaling and a novel molecular player in endothelial dysfunction and cardiovascular disease." (PMID 31319588, 2019). "We have previously demonstrated that mice with global haploinsufficiency of the insulin receptor [insulin receptor knockout (IRKO) mice] are normoglycemic yet have endothelial dysfunction and impaired endothelial repair." (PMID 29796592, 2018).
breast tumors (14 papers, 2010 to 2025). "On the other hand and given the well-documented involvement of INSR in various types of cancer, in particular breast tumors, experts in the field advise the combined targeting of both IGF1R and INSR." (PMID 27446805, 2016). "Yet, ER status could still be an important factor in inducing heparanase expression in breast tumors, therefore contributing to the occurrence of INSR-heparanase interplay under diabetic state." (PMID 28038446, 2017). "Interestingly, TCGA analysis of human breast tumors revealed a positive correlation between IGF1R and INSR expression." (PMID 36568144, 2022). "Unfortunately, antibodies targeting staining of the INSR and other proteins in the PI3K and MAPK pathway (such as AKT and p-P70S6K) did not work on our series of human breast tumor samples, as explained in the methods." (PMID 29486734, 2018).
cardiac hypertrophy (14 papers, 2012 to 2025). "Leading kinases included AKT1, MAPK1, MYLK, INSR, and ABL1, all of which are implicated in stress response and cardiac hypertrophy, particularly under physiological conditions." (PMID 40725470, 2025). "Cardiac hypertrophy in mice is characterized by chronic activation of growth-promoting signaling pathways downstream of the insulin receptor, with increased activation of AKT and SGK1 contributing to a hypertrophic response in various conditions." (PMID 32990683, 2020). "During hypertrophic stress, increased C/EBPβ downregulates the mir15a/mir16‐1 cluster, resulting in up‐regulation of multiple target proteins (INSR, IGF1R, AKT3, SGK1) in cardiomyocytes, causing increased activation of insulin/IGF1 signaling, ultimately causing cardiac hypertrophy and dysfunction." (PMID 33377640, 2020). "Preservation of insulin receptor and Akt levels in the rosiglitazone-treated diabetic myocardium might thereby confer protection against pathological cardiac hypertrophy." (PMID 24447392, 2014). "Taken together, these data suggest INSR, IGF1R, AKT3 and SGK1 are novel target genes contributing to mir15a/mir16‐1 inhibition‐mediated cardiac hypertrophy." (PMID 33377640, 2020). "g. insulin-like growth factor-1 or insulin receptor), leads to cardiac hypertrophy but is not accompanied by cardiac dysfunction." (PMID 23226508, 2012).
melanoma (13 papers, 2013 to 2023). A malignant, usually aggressive tumor composed of atypical, neoplastic melanocytes. "We next examined that survival curves of melanoma patients from the TCGA data set for patients with a BRAF mutation along with high or low levels of INSR or IGF1R." (PMID 34831014, 2021). "Both IGF-1Ri agents used here also inhibit INSR, and it would be informative to measure INSR expression in the melanoma cell line panel, to assess the contribution of this receptor to chemo-resistance." (PMID 26497996, 2015). "Similarly, IGF1R/Insulin Receptor (IR) expression increased in D/T combination-resistant melanoma cells in correlation with poor patient survival." (PMID 37834284, 2023). "Overall, these data indicate that the BRAF pathway inhibitor resistant cells have elevated IGF1R at the mRNA level and melanoma patients with elevated IGF1R and INSR have a worse survival compared to patients with low levels of IGF1R." (PMID 34831014, 2021).
Myotonia (13 papers, 2012 to 2025). An involuntary and painless delay in the relaxation of skeletal muscle following contraction or electrical stimulation. "For example, aberrant splicing of the muscle-specific chloride channel CLCN1 and the insulin receptor (INSR) accounts for myotonia in DM." (PMID 28623239, 2017). "For instance, in DM1-affected skeletal muscle, mis-splicing of chloride ion channel CLCN1 causes myotonia and misregulated splicing of Ca2+ pump CACNA1S and insulin receptor INSR transcripts likely contribute to muscle weakness and insulin resistance, respectively." (PMID 36499107, 2022). "Among the mis-splicing events that have been documented, splicing reversions occurring in the muscle chloride channel CLCN1, the insulin receptor INSR and BIN1 contribute respectively to myotonia, insulin resistance and muscle weakness." (PMID 25211016, 2014). "Particularly, missplicing of muscle chloride channel (CLCN1), insulin receptor (INSR), bridging integrator 1 (BIN1) and calcium channel voltage-dependent L type alpha 1S subunit (CACNA1S) results in myotonia, insulin resistance and muscle weakness, respectively, constituting key hallmarks of DM." (PMID 25183524, 2014).
ovarian carcinoma (13 papers, 2004 to 2025). A malignant neoplasm originating from the surface ovarian epithelium. "For example, in A-673, the combination of Linsitinib, an IGF-1R and insulin receptor inhibitor, with Paclitaxel has shown improved outcomes in refractory ovarian cancer patients." (PMID 41405961, 2025). "Increased expression and activation of various members of HER family receptors are observed after treatment with IGF-IR/InsR inhibitor in ovarian cancer cells, suggesting that up-regulation of HER pathway is sufficient to mediate resistance to IGF-IR-targeted therapy." (PMID 28137302, 2017). "Ovarian cancer cells resistant to saracatinib display activation of the MAPK pathway via reduced NF1 expression or overexpression of HER2 and the insulin receptor." (PMID 34856074, 2022). "In our study, we identified the genes with a mutation frequency ranking in the top 5 of 100 PTK genes in EOC, namely, MST1R, INSR, RET, PDGFRB, and PTK7, among which we studied the overlooked oncogenic role of RET in ovarian cancer." (PMID 32293499, 2020). "Insulin receptor has been previously reported overexpressed on OSPC and to be able to mediate a proliferative response in ovarian cancer cells." (PMID 15208622, 2004).
thyroid cancer (13 papers, 2012 to 2024). "Overexpression of IGF-1, IGF-1R, IGF-2 and insulin receptor (IR) can be seen in the early stage of thyroid cancer." (PMID 35711846, 2022). "Furthermore, other tumors, including colon, ovary and thyroid cancers, express the insulin receptor in high levels." (PMID 38814364, 2024). "Thyroid cancer cells also over-express the insulin receptor (IR), especially isoform IR-A." (PMID 38146457, 2023). "It has been shown that insulin-like growth factor (IGF)-1 and its receptor and insulin receptor was found in thyroid cancer, suggesting that insulin receptor overexpression may play a role in the etiopathogenesis of thyroid tumorigenesis." (PMID 30233494, 2018). "In addition, thyroid cancer tissues had higher insulin receptor levels." (PMID 37374075, 2023).
acanthosis nigricans (12 papers, 2013 to 2025). A melanotic cutaneous lesion that develops in the axilla and other body folds. "In conclusion, we report a case of a patient with RMS presenting with extensive acanthosis nigricans (AN) and carrying novel mutations in the INSR gene." (PMID 40309171, 2025). "In this report, we describe a Chinese female patient with RMS who carries two novel mutations in the INSR gene and presents with generalized acanthosis nigricans and hyperinsulinism." (PMID 40309171, 2025). "Heterozygous variants in the INSR gene have been associated with insulin-resistant diabetes mellitus accompanied by acanthosis nigricans (OMIM: 610549) and familial hyperinsulinemic hypoglycemia type 5 (OMIM: 609968), both inherited in an autosomal dominant manner." (PMID 39859454, 2025).
Anxiety (12 papers, 2014 to 2025). Intense feelings of nervousness, tension, or panic often arise in response to interpersonal stresses. "Insulin receptor knockout in the hippocampus of mice results in depression and anxiety-like behaviors, impaired cognition and metabolic abnormalities." (PMID 36038539, 2022). "Data from animal models show that brain-specific knockout of insulin receptor (NIRKO) in mice promotes age-related anxiety and depressive-like behavior through an alteration in dopamine turnover." (PMID 34408637, 2021). "Insulin receptor knockdown in the hypothalamus triggered anxiety and depressive like behaviors in rodent models." (PMID 34121997, 2021).
diabetic nephropathy (12 papers, 2014 to 2025). "Our findings are in contrast to reports from mice, where specific deletion of the insulin receptor is associated with marked albuminuria and histological features reminiscent of diabetic nephropathy, as well as enhanced sodium reabsorption." (PMID 25358339, 2014). "In models of diabetic kidney disease, excessive SMPDL3B expression impairs ceramide-1-phosphate synthesis and insulin receptor signaling, accelerating podocyte injury and glomerular decline." (PMID 41009450, 2025). "Here we report that SMPDL3b excess, as observed in podocytes in diabetic kidney disease (DKD), impairs insulin receptor isoform B-dependent pro-survival insulin signaling by interfering with insulin receptor isoforms binding to caveolin-1 in the PM." (PMID 31217420, 2019). "Defective insulin receptor signaling resulting from IR can induce a pathological condition similar to diabetic nephropathy, even in the absence of high blood glucose levels." (PMID 37653418, 2023). "Patients with the milder ‘type A’ form of INSR dysfunction who have hyperinsulinemic diabetes mellitus may develop features of diabetic nephropathy, yet have not been reported to show nephrocalcinosis even when observed for many years." (PMID 25358339, 2014).
endometrial cancer (12 papers, 2007 to 2025). Primary or metastatic malignant neoplasm involving the endometrium (mucous membrane that lines the endometrial cavity). "The invasion behavior of endometrial cancer is associated with the activation of the insulin receptor IRS1." (PMID 39205919, 2024). "The likely pathomechanism of endometrial cancer development associated with vaspin is related to stimulation of the insulin receptor (IR), as well as PI3K/AKT and MAPK/ERK signaling pathways." (PMID 37190027, 2023). "Visfatin has also been shown to significantly affect the progression of malignant endometrial cancer via activation of the insulin receptor (IR) and PI3K/AKT and MAPK/ERK signaling pathways." (PMID 37190027, 2023). "There is evidence for a direct effect on endometrial cancer cells of insulin and IGF-1; activation of the insulin receptor causes an increase in cell proliferation and inhibition of apoptosis through both the MAPK and PI3K/Akt pathways." (PMID 34359595, 2021). "In a study on endometrial cancer cell lines, it was found that VIS stimulated cell proliferation and inhibited apoptosis through the activation of the INSR, AKT/PI3K, and MAPK/ERK1/2 signaling pathways." (PMID 38132154, 2023). "Furthermore, the insulin receptor expression and IGF-1 signaling synergistically contribute to the development of endometrium cancer in PCOS population." (PMID 35356614, 2022). "Studies have shown that visfatin can upregulate the expression of IR and insulin receptor substrate (IRS) 1/2, and it can coactivate the PI3K/Akt and MAPK/ERK1/2 signaling pathways with insulin to promote the proliferation and inhibit apoptosis of endometrial cancer cells." (PMID 31440472, 2019).
glioma (12 papers, 2015 to 2024). A benign or malignant brain and spinal cord tumor that arises from glial cells (astrocytes, oligodendrocytes, ependymal cells). "The 83-14 antibody targeting the insulin receptor has markedly increased the delivery of liposomes containing antisense oligonucleotides to gliomas." (PMID 39204177, 2024). "Involvement of the AKT pathway in GBM pathogenesis is also connected to activation of the insulin receptor (InsR) that promotes proliferation and survival of glioma cells both in an insulin-dependent and -independent manner." (PMID 33604294, 2020). "The insulin receptor, expressed at the BBB and on glioma cell membranes, along with the epidermal growth factor receptor (EGFR) found in brain tumor cells, are key targets for brain delivery via immuno-liposomes." (PMID 39204177, 2024). "We have found that IGF2R, INSR, and IGF1R have a tight relationship with SOX10 in gliomas." (PMID 36524115, 2022). "Zinc-inhibition of the PTPs 1B and SHP-1 (IC50 values: 17 and 93 nM, respectively) in C6 rat glioma cells resulted in increased phosphorylation of the insulin receptor and the insulin receptor substrate, without affecting activity of the corresponding kinases." (PMID 33662875, 2021). "In particular, resistance to EGFR inhibition in human glioma cells was attributed to compensatory signaling by IGF-IR, and insulin receptor/IGF-IR signaling was shown to confer resistance to Gefitinib in EGFR-dependent glioblastoma, through compensatory AKT activation." (PMID 33072581, 2020). "It turned out that dual insulin-like growth factor 1 receptor/insulin receptor (IGF1R/IR) kinase inhibitors, BMS-754807 (BMS) and linsitinib (LIN), effectively inhibited the proliferation of glioma cells without negatively affecting CAR-T cells." (PMID 38339374, 2024).
Impaired glucose tolerance (12 papers, 2008 to 2024). An abnormal resistance to glucose, i.e., a reduction in the ability to maintain glucose levels in the blood stream within normal limits following oral or intravenous administration of glucose. "This may occur due to increased diacylglycerol, an activator of protein kinase C (PKC) which causes decreased tyrosine phosphorylation of the insulin receptor, increased glucose production, and impaired glucose tolerance." (PMID 29287121, 2017). "Similar to our findings, LIRKO mice also showed improved glucose tolerance during ageing (impaired glucose tolerance at 2 months of age and normal glucose tolerance at 6 months of age), suggesting that insulin receptor signaling is altered during ageing as an adaptation." (PMID 28556799, 2017). "Administration of safranal (20 mg/kg, PO, for 2 weeks) led to dephosphorylation of the insulin receptor via inhibition of protein tyrosine phosphatase 1B (PTP1B), which plays a role in insulin signaling and improved impaired glucose tolerance." (PMID 38419885, 2024). "Despite the clear signs of impaired glucose tolerance found in both, the GTT and the ITT, expression of insulin receptor (Ir) and insulin receptor substrate 2 (Irs2) mRNA was similar between both groups in muscle and liver tissue." (PMID 32881925, 2020). "CILP-2 overexpression resulted in impaired glucose tolerance and hepatic IR in vivo and increased PEPCK expression whereas suppressed phosphorylation of insulin receptor and Akt kinase in vitro." (PMID 30896018, 2019). "Interestingly, the ablation of insulin receptor in white adipose tissue (FIRKO mice) also resulted in an improved metabolic state during ageing, since FIRKO mice were protected against ageing-induced impaired glucose tolerance." (PMID 28556799, 2017).
Leprechaunism (12 papers, 2010 to 2025). "On the other hand, in patients with leprechaunism there are functional abnormalities of the EGF receptor, as well as of the insulin receptor, coined as multiple growth factor-resistant syndrome, that may contribute to the severity of the syndrome." (PMID 20184722, 2010).
dementia (11 papers, 2012 to 2024). Loss of intellectual abilities interfering with an individual's social and occupational functions. "Defects in the insulin receptor signaling are reported to be associated with decreased cognitive function and the development of dementia, including AD." (PMID 30400348, 2018). "G. M. Pasinetti and colleagues describe the role of insulin receptor (IR) signaling mechanisms in the onset and/or progression of AD dementia and the relevance of insulin-sensitizing therapeutic strategies to stimulate down-stream IR in nondiabetic AD patients." (PMID 22970405, 2012). "Recent research has also reported that mechanisms seen in dementia such as Aβ, Tau and insulin receptor pathways may all play important roles in the ganglion cell loss seen in glaucoma and that these pathways may be similar or overlap with those seen in AD49,50." (PMID 35688899, 2022).